CAT (catalase)
Diseases named in the same sentence as CAT in open-access papers (continued):
Sharing a sentence is not in itself a finding about the gene and the disease.
Myocardial fibrosis (5 papers, 2017 to 2025). "EAT-CM through miR-134-5p/KAT7/MnSOD/catalase axis and increase in ROS intracellular levels promoted activation of cardiac fibroblasts into myofibroblasts.Knockdown of miR-134-5p limited myocardial fibrosis in vivo." (PMID 38612394, 2024). "Upregulated antioxidant capacity through a mitochondrial specific overexpression of catalase protected against features of cardiac ageing including myocardial fibrosis." (PMID 28919427, 2017). "Also, the cardiac histopathology, myocardial oxidative stress markers (malondialdehyde (MDA), glutathione (GSH) and CAT) and norepinephrine (NE), myocardial fibrosis, the expression of caspase-3, TGF-β, TNF-α, and tyrosine hydroxylase (TH) in myocardial tissues were measured." (PMID 32106580, 2020). "In the male Wistar rats treated with 1 mg/kg of LPS for three weeks, thymoquinone at 2, 5, and 10 mg/kg doses also could improve myocardial fibrosis through decreasing the cardiac level of IL‐1β, TNF‐α, NO, and MDA, and enhancing the total thiol content and SOD and CAT activity." (PMID 39898124, 2025).
non-small cell lung carcinoma (5 papers, 2016 to 2022). A group of at least three distinct histological types of lung cancer, including non-small cell squamous cell carcinoma, adenocarcinoma, and large cell carcinoma. "Increased CAT levels were found in patients with non-small cell lung cancer compared to controls." (PMID 26754536, 2016). "It was reported that a 95% ethanolic extract prepared from the whole C. gigantea plant induced apoptotic cell death through the upregulation of ROS production by suppressing the ROS scavenger superoxide dismutase 2 and catalase in A549 and NCI-H1299 non-small cell lung cancer cells." (PMID 34343190, 2021). "However, in another small-scale study with non-small cell lung cancer (n = 50), plasma GPx, SOD and CAT were significantly reduced in patients, but beta-carotene was significantly increased compared to healthy controls in the later stage of the disease (n = 16)." (PMID 31213029, 2019).
osteonecrosis (5 papers, 2022 to 2023). A none disease characterized by death of bone tissue due to a lack of blood supply. "Nevertheless, a Korean search group showed a strong association of CAT SNVs with osteonecrosis of the femoral head from various causes, which sheds light on the role of CAT polymorphisms in bone metabolism." (PMID 37107290, 2023). "In this study, according to the ANOM test; MDA activity was above the upper decision line, SOD and GSH activities were located on the decision lines, and CAT activity was below the lower decision line in Osteonecrosis patients." (PMID 35720997, 2022). "In patients with osteonecrosis and X-ray exposure; high values of MDA level (2.999–4.9980) were associated with low levels of SOD (1.4-3.235), CAT (0.0010-0.0644) and GSH (0.0051-0.0097)." (PMID 35720997, 2022). "In the femur, MDA concentration increased while catalase SOD activity and GSH level decreased, expressing the establishment of oxidative stress in ethanol-induced osteonecrosis." (PMID 37416805, 2023).
psychosis (5 papers, 2011 to 2025). "Additionally, an increasing dosage of the CAT rs1001179 c.-262 T allele was associated with a higher frequency of psychosis." (PMID 40725019, 2025). "Antioxidant markers such as catalase and nitrite exhibited changes during the clinical course of patients, being lower at first-episode psychosis (FEP) and then increased in patients with exacerbation of psychosis and under pharmacological treatment." (PMID 36092733, 2022). "Moreover, in the patient group, age of onset of psychosis, duration of illness, and dose of antipsychotic drugs were not correlated with the MDA level or with MnSOD, CAT and GSH-Px activities (all P > 0.05)." (PMID 35757215, 2022).
retinal degeneration (5 papers, 2016 to 2022). Degeneration of the retina. "These glutathione pool measurements, together with the retinal degeneration assessment in the fly line used in the current study, support a neuroprotective role for Catalase overexpression in photoreceptors in both light stress and aging models." (PMID 35205309, 2022). "We attribute the differences in severity/onset of the retinal degeneration in the flies used in the current study (Rh1-GFPKASH 3–1) versus the previous lines used (w1118 or cn bw) to the high levels of Catalase expressed in photoreceptors resulting from the insertion position of the transgene." (PMID 35205309, 2022). "The observed retinal degeneration could reflect a marked excess of ROS that exceeded the protective capacities of incretins, catalase, and other endogenous antioxidants." (PMID 34440748, 2021). "Since the Rh1-GFPKASH 3–1 flies are viable, and homozygous lines do not exhibit premature retinal degeneration, Catalase expression is unlikely to be disrupted in these flies." (PMID 35205309, 2022). "It is interesting that Catalase expression correlates with protection against blue light stress because overexpression of Superoxide dismutase 1 (Sod1) decreases H2O2 levels in the eye but does not protect against blue light-induced retinal degeneration." (PMID 35205309, 2022).
systemic lupus erythematosus (5 papers, 2008 to 2022). An autoimmune multi-organ disease typically associated with vasculopathy and autoantibody production. "CAT levels have been reported to be lower in the serum of patients with systemic lupus erythematosus compared to healthy controls, including an association with the CC genotype." (PMID 36555526, 2022). "Catalase is located on chromosome 11p13 where linkage analysis has revealed a marker in the same region of the genome among families with thrombocytopenia, a clinical manifestation associated with severe lupus in SLE affected pedigrees." (PMID 18606005, 2008). "In particular, increased SOD activity and malondialdehyde (MDA) levels, the most frequently used biomarkers of oxidative stress, as well as a decrease in CAT and glutathione peroxidase enzymes in the serum of systemic lupus erythematosus patients, have also been reported." (PMID 36555526, 2022). "A reduction in the activity of CAT in serum was found in anti-GBM-GN, and a significant decrease in the activity of GPX was observed in patients with systemic lupus erythematosus (SLE)." (PMID 24480247, 2014).
acute myeloid leukemia (4 papers, 2016 to 2018). Acute myeloid leukemia (AML) is a group of neoplasms arising from precursor cells committed to the myeloid cell-line differentiation. "The direct role of H2O2 in the induction of apoptosis in acute myeloid leukemia (AML) cells has been confirmed using catalase to completely abrogate vitamin C-induced apoptosis." (PMID 29971019, 2018). "The purpose of the study was to evaluate the association between CAT C262T, GPX1 Pro198Leu, MnSOD Ala16Val, GSTM1, GSTT1, and GSTP1 Ile105Val gene polymorphisms and acute myeloid leukemia risk, in a case-control study comprising 102 patients and 303 controls." (PMID 26823947, 2016). "Interestingly, we observed reduced expression of another set of antioxidant proteins: catalase (CAT) and glutathione S-transferase P, as previously observed in resistant acute myeloid leukemia cells." (PMID 27527861, 2016). "It was confirmed that acute lymphocytic leukemia (ALL) and acute nonlymphocytic leukemia (ANLL) have increased levels of various reactive oxygen (ROS) such as superoxide radicals, H2O2, and decreased levels of enzymatic (SOD and CAT) and nonenzymatic antioxidants compared to healthy individuals." (PMID 29387293, 2017).
AIDS (4 papers, 2021 to 2022). A syndrome resulting from the acquired deficiency of cellular immunity caused by the human immunodeficiency virus (HIV). "The Abs of healthy donors and animals, as well as patients with AIDs, possess not only peroxidase but also catalase, superoxide, dismutase, and H2O2-independent oxidoreductase activities." (PMID 36364362, 2022). "Antibodies from healthy donors and animals, as well as from patients with AIDs, have not only peroxidase, but also H2O2-independent oxidoreductase, catalase, and superoxide dismutase activities." (PMID 33916567, 2021). "Lower GSH levels were found as HIV advances to acquired immunodeficiency syndrome (AIDS) and alterations in antioxidant defense systems (SOD, CAT, and GPX) have also been observed in PLWH." (PMID 35008706, 2021).
alcohol abuse (4 papers, 2021 to 2025). The use of alcoholic beverages to excess, either on individual occasions ("binge drinking") or as a regular practice. "CAT acts as an antioxidant enzyme and protects against the deleterious effects of free radicals, but alcohol abuse also significantly reduces its activity." (PMID 34681429, 2021). "In addition, alcohol abuse decreased SOD, CAT, and GPx activities and GSH level." (PMID 34834064, 2021).
babesiosis (4 papers, 2014 to 2023). Babesiosis refers to a condition caused by microscopic parasites that infect the red blood cells. "Comparable results were observed in dogs with uncomplicated babesiosis caused by B. canis, with increased activities of superoxide dismutase and catalase and decreased concentrations of zinc and copper in the blood of affected dogs." (PMID 36839438, 2023). "However, even dogs with uncomplicated babesiosis had significantly lower activities of superoxide dismutase and catalase than healthy dogs." (PMID 36839438, 2023). "Babesia infection induced oxidative stress in spleen as evidenced by the decreased GSH, CAT concentration as well as increased formation of lipid peroxidation, and nitrite/nitrate." (PMID 25136591, 2014). "However, dogs with MODS showed significantly lower (P < 0.01) activities of catalase, SOD and GPx and significantly higher (P < 0.01) MDA concentrations compared to dogs with uncomplicated babesiosis." (PMID 28438201, 2017).
Bovine mastitis (4 papers, 2013 to 2024). INFLAMMATION of the UDDER in cows. "Catalase activity is a marker of bovine mastitis, which plays a central role in milk redox control and markedly increases during the pathophysiology of bovine CM." (PMID 32582039, 2020).
coccidiosis (4 papers, 2019 to 2023). A parasitic infection caused by Coccidia. "Coccidiosis in chickens involves oxidative stress and reduces antioxidant enzymes including SOD, catalase, and GPx, which is also demonstrated in the present study." (PMID 36903445, 2023). "Coccidiosis vaccine challenge or dietary treatments did not affect the concentrations of catalase, SOD, or TAC in serum samples." (PMID 32183035, 2020). "According to the expression functions of PCo1, BWG3–5 and the concentrations of CAT, SOD and IFN-γ had higher coefficient in the equation, which suggested that the four indicators could also indirectly reveal the level of coccidiosis resistance." (PMID 31698877, 2019).
dengue (4 papers, 2017 to 2025). "We already show that catalase, an antioxidant protein, is up-regulated in severe dengue patients, indicating a possible scenario of oxidative stress in response to infection." (PMID 32286360, 2020). "In particular, expression levels of endogenous antioxidant genes including catalase (CAT), manganese superoxide dismutase (MnSOD), and glutathione peroxidase (GPX) were found to be downregulated in dengue patients." (PMID 33807863, 2021).
dental caries (4 papers, 2022 to 2023). The decay of a tooth, in which it becomes softened, discolored, and/or porous. "In addition, most articles have evaluated TAC as the main parameter of biochemical changes in the saliva of patients with dental caries, and parameters such as glutathione, superoxide dismutase, uric acid, catalase, lipid peroxidation, and nitric oxide." (PMID 36829890, 2023). "In this systematic review, these articles investigate the parameters associated with the modulation of antioxidant defenses (TAC, GSH, vitamin C, SOD, UA, and CAT) and pro-oxidants (LPO and NO) in the saliva of patients with dental caries." (PMID 36144263, 2022). "The knowledge that C. albicans’ catalase protects S. mutans in close contact with H2O2 stress highlights the importance of developing strategies that target the disassociation of these partners in grime for the successful prevention and treatment of dental caries." (PMID 37607054, 2023).
Down syndrome (4 papers, 2020 to 2025). "Similarly, the SOD/(GPx + CAT) ratio is greater in the erythrocytes of Down syndrome patients than in those of controls, which may result in increased production of H2O2." (PMID 39273262, 2024). "In high-oxidative-stress conditions, such as Down’s syndrome (DS), increased activities of SOD and GPx and reduced activity of CAT in erythrocytes are evident." (PMID 33946757, 2021).
duodenal ulcer (4 papers, 2014 to 2025). An ulcer in the duodenal wall. "The results showed that the administration with TCOPs significantly reduced gastric and duodenal ulcer index, increased gastric juice pH, superoxide dismutase (SOD), catalase (CAT), and glutathione peroxidase (GSH-Px) activities, along with the reduction of malondialdehyde (MDA) contents." (PMID 34204516, 2021).
fluorosis (4 papers, 2010 to 2023). "The serum CAT activity of the rats in the fluorosis group was lower than that of the control group, and gastrodin also significantly increased the decreased CAT level caused by fluoride." (PMID 33010109, 2020). "In such subjects, the clinical signs of fluorosis appear accompanied by alterations in the enzyme activity of SOD, catalase, and Glpx, in addition to an increase in MDA levels in the serum or fatty acids of the tissues." (PMID 20640162, 2010). "Wistar rats were given different doses of gastrodin 1 month after fluoride administration, and samples of blood, bone and teeth were collected after 2, 3 and 4 months; glutathione peroxidase glu, CAT and SOD levels in the fluorosis group were lower than those in the control group." (PMID 33010109, 2020). "Concerning enzymatic activity, the results showed that catalase and SOD activities were significantly lower in female (p < 0.0001) and male (p < 0.0001) lambs reared in endemic fluorosis area (Group II) compared to those reared in fluorosis-free area (Group I)." (PMID 37803131, 2023).
gastric adenocarcinoma (4 papers, 2021 to 2026). "Less human CAT activity was noted in gastric adenocarcinoma and in CD, where patients showed a permanent suppression of CAT activity in their mononuclear cells." (PMID 33430270, 2021). "A decrease in the activity of CAT has been recorded in patients with gastric adenocarcinoma." (PMID 35626358, 2022). "In the present study, we have investigated the effects of LPE on the human gastric adenocarcinoma AGS and MKN-28 cells and on the activity of a crucial redox enzyme, catalase (CAT)." (PMID 41596250, 2026). "To verify the in vitro inhibition by the LPE of key redox enzymes (CAT, SOD-1/2, and MAO-A) in the gastric adenocarcinoma cells, we assessed changes in the protein expression of these enzymes after LPE treatment." (PMID 41596250, 2026).
gastric tumour (4 papers, 2016 to 2023). "Moreover, JS‐K administration also significantly suppressed the expression of SOD1 and catalase in gastric tumour tissues, indicating that JS‐K down‐regulates SOD1 and catalase in vivo." (PMID 30672108, 2019). "Moreover, JS‐K administration (1.5 and 3 mg/kg) significantly decreased SOD1 and catalase activity in gastric tumour tissues; therefore, JS‐K could decrease SOD1 and catalase activity in vivo and in vitro, which would also contribute to JS‐K‐induced ROS accumulation." (PMID 30672108, 2019).
gastritis (4 papers, 2014 to 2025). Inflammation of the stomach. "Likewise, catalase (CAT) concentrations decreased in gastritis, causing accumulation of toxic hydrogen peroxide and worsening inflammation." (PMID 41302134, 2025). "Administration of CAW reduced acute gastritis by decreasing MDA levels and increasing the components of the antioxidant system including GSH and catalase." (PMID 26483844, 2015). "However, patients with gastritis and H. pylori on OME therapy showed significant increase in catalase compared to the other groups." (PMID 35436881, 2022). "pylori, they presented catalase increases in relation to patients without gastritis and were not taking OME." (PMID 35436881, 2022). "CAW showed a protective effect on ethanol-induced gastritis and may be a candidate for gastritis therapy because it inhibits lipid peroxidation and increases levels of GSH, catalase, GST, and PGE2." (PMID 26483844, 2015). "The negative correlations with antioxidant enzymes (CAT and GPX) indicate that the depletion of the antioxidant defense system contributes to ERK/MMP-10, signaling activation during gastritis." (PMID 41302134, 2025). "In patients with gastritis and H. pylori on OME therapy, positive correlations were observed between micronucleus induction with catalase and superoxide dismutase measurements, and negative correlation for picnoses induction." (PMID 35436881, 2022).
glomerulosclerosis (4 papers, 2012 to 2023). A hardening of the kidney glomerulus caused by scarring of the blood vessels. "Glomerulosclerosis, albuminuria, and lipid peroxidation in renal tissue were found to be more severe in mice deficient in catalase than in wild-type mice after doxorubicin injection." (PMID 26063968, 2015). "In our study, the deficiency of catalase accelerated the albuminuria and glomerular sclerosis in the ADR nephropathy model." (PMID 22443450, 2012). "We herein demonstrated that ADR induced more albuminuria and glomerulosclerosis in catalase-deficient mice." (PMID 22443450, 2012). "Further studies are needed to elucidate whether and how a low catalase activity in humans influences either albuminuria or glomerulosclerosis associated with kidney diseases." (PMID 22443450, 2012). "In the present study, we hypothesized that a defect in the antioxidant system in the form of catalase deficiency would enhance proteinuria, glomerular sclerosis, and eventually lead to the loss of renal function." (PMID 22443450, 2012). "A functional catalase deficiency was hypothesized to exacerbate albuminuria and the progression of glomerulosclerosis in this model." (PMID 22443450, 2012). "Treatment with catalase supplementation may contribute to the suppression of progressive renal injury with proteinuria and glomerulosclerosis." (PMID 22443450, 2012). "Collectively, these data suggest that the increased ROS, particularly the hydroxyl radical, resulting from the reduction of catalase activity, may be involved in the acceleration of glomerulosclerosis found under acatalasemic disease conditions." (PMID 22443450, 2012). "It is unknown whether albuminuria and glomerulosclerosis are related to low catalase activity in humans, although the total antioxidant capacity is correlated with albuminemia, and inversely correlated with proteinuria and anti-DNA antibodies in subjects with lupus nephritis." (PMID 22443450, 2012).
hearing loss (4 papers, 2017 to 2025). "Sod2, catalase, and peroxiredoxin which contains free radicals have been known to have an essential role in the cochlea in noise-induced hearing loss (NIHL)." (PMID 29220389, 2017). "Interestingly, polymorphisms in the gene encoding catalase have been linked to an increased susceptibility to hearing loss in humans, and mice that are heterozygous for a mutation in Sod1 gene show an increased vulnerability to hearing loss induced by noise exposure." (PMID 30090654, 2018).